RNPEP (arginyl aminopeptidase)
Description:
Exopeptidase which selectively removes arginine and/or lysine residues from the N-terminus of several peptide substrates including Arg(0)-Leu-enkephalin, Arg(0)-Met-enkephalin and Arg(-1)-Lys(0)- somatostatin-14. Can hydrolyze leukotriene A4 (LTA-4) into leukotriene B4 (LTB-4) (By similarity).
Synonyms: AP-B; APB
Tractability: Small molecule: a drug acting on it is in phase 2 or 3 trials; it belongs to a druggable protein family. Antibody: its Gene Ontology location is reachable by antibodies, with high confidence; UniProt places it where antibodies can reach, with medium confidence. PROTAC: ubiquitination databases record sites on it; its protein half-life has been measured; a small molecule that binds it is known.
Target class: Protease; Enzyme; Metallo protease; Metallo protease MAE clan; Metallo protease M1 family
Gene: Protein-coding gene on chromosome 1 (201,982,372 to 202,006,147, forward strand). Ensembl gene ENSG00000176393.
Subcellular location: Secreted
Subcellular location (Human Protein Atlas): Golgi apparatus; End piece; Principal piece; Predicted to be secreted
Gene Ontology:
Molecular function: aminopeptidase activity; epoxide hydrolase activity; metalloaminopeptidase activity; metalloexopeptidase activity; zinc ion binding; metallopeptidase activity
Biological process: proteolysis
Cellular component: extracellular exosome; extracellular region; plasma membrane
Genetic constraint (gnomAD): Loss-of-function variants: 38 observed, 51.9 expected, observed/expected ratio (o/e) 0.73, 90% interval 0.56 to 0.96. The upper end of that interval is the gene's LOEUF score, 0.96, which puts it in group 4 of 6, group 1 being the genes least tolerant of losing a copy. Missense variants: 533 observed, 608.85 expected, observed/expected ratio (o/e) 0.88, 90% interval 0.81 to 0.94. Synonymous variants: 206 observed, 237.49 expected, observed/expected ratio (o/e) 0.87, 90% interval 0.77 to 0.97.
Homologues: Orthologues: chimpanzee RNPEP (99% identical), macaque RNPEP (98% identical), dog RNPEP (89% identical), guinea pig RNPEP (89% identical), mouse Rnpep (89% identical), rat Rnpep (88% identical), pig RNPEP (87% identical), rabbit RNPEP (80% identical), tropical clawed frog rnpep (65% identical), zebrafish rnpep (61% identical), Drosophila melanogaster SP1029 (18% identical), Drosophila melanogaster CG31445 (17% identical), and 5 more. Paralogues in human: RNPEPL1 (46% identical), LTA4H (35% identical), AOPEP (25% identical), TRHDE (20% identical), ANPEP (20% identical), ERAP1 (19% identical), LVRN (18% identical), LNPEP (18% identical), ENPEP (18% identical), ERAP2 (18% identical), NPEPPS (16% identical).
Diseases named in the same sentence as RNPEP in open-access papers:
RNPEP is named in the same sentence as 19 diseases in open-access papers, as found by Europe PMC text mining. Sharing a sentence is not in itself a finding about the gene and the disease. The quoted sentences say what the papers report.
multiple myeloma (2 papers, 2021 to 2023). "A higher expression of the aminopeptidase genes XPNPEP1, RNPEP, DPP3, and BLMH in multiple myeloma plasma cells was associated with shorter patient overall survival." (PMID 33810334, 2021). "This compound, considered a pro-drug activated by aminopeptidases expressed in multiple myelomas (such as APN, leucyl aminopeptidase 3 (LAP3), arginyl aminopeptidase (RNPEP), and leukotriene A4 hydrolase (LTA4H)) has been studied in phase I/II (HORIZON, ANCHOR) and phase III (OCEAN) trials." (PMID 36979703, 2023). "Melflufen could be hydrolyzed to its active form by the aminopeptidases LAP3, LTA4H, RNPEP, and ANPEP, all of which are expressed in multiple myeloma." (PMID 33810334, 2021).
colorectal adenoma (1 paper, 2021). An adenoma that arises from the colon or rectum. "RNPEP (alias aminopeptidase B) mRNA levels have been demonstrated to be altered during colorectal adenoma–carcinoma evolution, and RNPEP plasma levels are also independent prognostic factors for colorectal cancer patients." (PMID 33810334, 2021).
thyroid neoplasms (1 paper, 2021). "Both XPNPEP1 and RNPEP enzyme activities were found to be significantly elevated in thyroid neoplasms when compared with nonmalignant adjacent tissues." (PMID 33810334, 2021).
RNPEP also shares sentences with these, for which no sentence is quoted: tumor (3 papers); Arthritis (1); breast carcinoma (1); carcinoma (1); cerebral infarct (1); colorectal cancer (1); dyslipidemia (1); endometriosis (1); epilepsy (1); fibromyalgia (1); glioma (1); infection (1); Infertility (1); ischemic stroke (1); nicotine dependence (1); Stroke (1).